TMEM265 (transmembrane protein 265)
Synonyms: IFITMD8
Gene: Protein-coding gene on chromosome 16 (30,740,642 to 30,745,196, forward strand). Ensembl gene ENSG00000281991.
Subcellular location: Membrane
Gene Ontology:
Cellular component: membrane
Genetic constraint (gnomAD): Loss-of-function variants: 8 observed, 8.58 expected, observed/expected ratio (o/e) 0.93, 90% interval 0.55 to 1.64. That is too few expected variants to judge how well the gene tolerates losing a copy. Missense variants: 152 observed, 146.78 expected, observed/expected ratio (o/e) 1.04, 90% interval 0.91 to 1.18. Synonymous variants: 53 observed, 57.49 expected, observed/expected ratio (o/e) 0.92, 90% interval 0.74 to 1.16.
Homologues: Orthologues: chimpanzee TMEM265 (98% identical), macaque TMEM265 (95% identical), dog TMEM265 (90% identical), pig TMEM265 (88% identical), rabbit TMEM265 (87% identical), guinea pig TMEM265 (85% identical).
Diseases named in the same sentence as TMEM265 in open-access papers:
TMEM265 is named in the same sentence as 2 diseases in open-access papers, as found by Europe PMC text mining. Sharing a sentence is not in itself a finding about the gene and the disease. The quoted sentences say what the papers report.
tumor (2 papers, 2021 to 2023). "The expression of GLB1L and TMEM265 was associated with the level of tumor-infiltrating immune cells (r > 0.4, p < 0.05)." (PMID 34692486, 2021).
TMEM265 also shares sentences with these, for which no sentence is quoted: colorectal cancer (1 paper).